AKT1 (AKT serine/threonine kinase 1)
Diseases named in the same sentence as AKT1 in open-access papers (continued):
Sharing a sentence is not in itself a finding about the gene and the disease.
leiomyosarcoma (4 papers, 2015 to 2024). An uncommon, aggressive malignant smooth muscle neoplasm, usually occurring in post-menopausal women. "Activated MTOR/AKT1 signaling, RASSF1 hypermethylation and MYC expression can also be found in a subset of leiomyosarcomas." (PMID 29881541, 2018).
liver cirrhosis (4 papers, 2022 to 2025). "Here, we showed AKT1 with a Degree of 156, Closeness of 0.4619, and Betweenness of 0.0403, a crucial protein target in liver cirrhosis." (PMID 36297027, 2022). "The focal adhesion pathway encompasses several genes, and KEGG analysis demonstrated that AKT1, CTNNB1, EGFR, FN1, JUN, and SRC were strongly related to curcumin compounds that might be influenced by liver cirrhosis in our study." (PMID 36297027, 2022).
lung neoplasm (4 papers, 2017 to 2026). A benign or malignant, primary or metastatic neoplasm involving the lungs. "In addition, lung neoplasms were associated with AKT1, lipoidosis was associated with ASNS, and drug-induced acute liver injury was associated with SHC1." (PMID 42065147, 2026). "For instance, SF(Pkinase, Death) contains seven members (MAP3K8, MAPK3, MAPK14, MAPK1, AKT1, CHEK2, and DAPK1) that are related to lung neoplasms." (PMID 31937869, 2020).
migraine (4 papers, 2021 to 2025). "Studies found that Akt1 is extensively involved in the regulation of microglia-mediated neuroinflammation, which leads to central sensitization and thereby triggers migraines." (PMID 41009787, 2025). "Based on our own RNA-sequencing data, genes previously known to link with migraine through genome-wide analysis or various migraine models, Crebbp, Trpm3, Zmynd8 and Akt1 are among the potential candidate genes that have especially caught our interest." (PMID 39390364, 2024). "We found expression induction of several migraine-related genes (Crebbp, Trpm3, Atp5α1 and Akt1) were downregulated by photophobia, notably this reduction was restored by SRCT in our study." (PMID 39390364, 2024).
pulmonary edema (4 papers, 2017 to 2025). Accumulation of fluid in the lung tissues causing disturbance of the gas exchange that may lead to respiratory failure. "Histamine, bradykinin, and des-arg-bradykinin receptor can all lead to increased endothelial permeability through AKT-1 activation, all of which can lead to pulmonary edema." (PMID 35345695, 2022).
uterine cancer (4 papers, 2006 to 2020). Primary or metastatic malignant neoplasm involving the uterine corpus and/or the cervix. "Lastly, patient P11 with uterine carcinoma harbored a truncal RAC-alpha serine/threonine-protein kinase (AKT1) E17K mutation in two out of two of her MRTB cores analyzed (only two of four cores had DNA of sufficient quality for analysis in her case)." (PMID 32560395, 2020).
vascular tumor (4 papers, 2017 to 2022). "However, in vascular tumour cells AKT3 depletion increases whereas AKT1 depletion decreases sprouting angiogenesis and wound healing capacity, suggesting that AKT3 conversely inhibits vascular tumour growth and migration." (PMID 28082369, 2017). "In a previous experimental study with mice, AKT1 promoted de novo tumor formation, while AKT3 inhibited vascular tumor growth." (PMID 36286049, 2022).
alopecia (3 papers, 2021 to 2025). Hair loss usually from the scalp. "Screened common genes of Decursin and alopecia gene sets were CASP3, CASP7, CASP8, MAPK1, AKT1, and others." (PMID 34832932, 2021).
anxiety disorder (3 papers, 2022 to 2025). A category of psychiatric disorders which are characterized by anxious feelings or fear often accompanied by physical symptoms associated with anxiety. "The deficiency of activated AKT1 in laboratory animals resulted in functional and structural deviations in the prefrontal cortex and led to anxiety disorder or widespread cognitive behavioral deficits." (PMID 39410900, 2025).
autism spectrum disorder (3 papers, 2022 to 2025). A spectrum of developmental disorders that includes autism, and Asperger syndrome. "The altered AKT1-signalling pathway is also evident in ATM-associated autism spectrum disorders that may exaggerate COVID-1940." (PMID 36229517, 2022).
ciliopathies (3 papers, 2019 to 2024). "In human diseases with ciliopathies, such as polycystic kidney, the selective AKT1 inhibitor may have a unique application to promote cilia formation." (PMID 30850948, 2019).
endometrial tumor (3 papers, 2015 to 2019).
follicular lymphoma (3 papers, 2014 to 2017). Follicular lymphoma is a form of non-Hodgkin lymphoma characterized by a proliferation of B cells whose nodular structure of follicular architecture is preserved. "AKT1-independent activation of mTOR has been reported in several cell types, including B-lymphocyte cell lines and follicular lymphoma cells." (PMID 25769101, 2015).
Giardia infection (3 papers, 2021 to 2024). "Examining the mean expression of the four genes AKT1, CDKN2A, KRAS, and PIK3CA showed that three genes of AKT1, CDKN2A, and KRAS had increased expression in people with a history of giardiasis compared to healthy people." (PMID 38170269, 2024).
granulosa cell tumor (3 papers, 2018 to 2025). A slow-growing, malignant tumor, characterize by the presence of granulosa-like cells and Call-Exner bodies, that is almost always found in the ovary. "In addition to AKT1 mutations, an activating mutation R201C or R201H of the stimulatory g protein (GαS) was observed in about one third of juvenile granulosa cell tumors." (PMID 29389895, 2018). "A recent study reported in-frame duplications within the oncogene AKT1 in >60% of granulosa cell tumors." (PMID 29389895, 2018).
hemangioma (3 papers, 2017 to 2022). A benign vascular lesion characterized by the formation of capillary-sized or cavernous vascular channels. "In our study, the AKT1 gene encoding RAC (Rho family)-alpha serine/threonine-protein kinase was upregulated in proliferating hemangioma." (PMID 35740845, 2022). "The pictures provided by the authors include human hemangioma tissue with proliferating hemangioma morphology and high AKT1 immunohistochemical expression." (PMID 35740845, 2022). "In our study, we detected an upregulation of MAPK14, a member of the MAPK family, in a case of proliferating hemangioma (not yet reported in the literature) together with AKT1 upregulation." (PMID 35740845, 2022). "AKT1, p38/MAPK14 (upregulated in proliferating hemangioma but downregulated in involuting hemangioma), and ACTA2 (upregulated in involuting hemangioma but downregulated in proliferating hemangioma) were found to have divergent expression in proliferating and involuting hemangiomas." (PMID 35740845, 2022). "Proliferating hemangioma had MAPK14 and AKT1 gene upregulation and ACTA2 downregulation." (PMID 35740845, 2022).
hepatocellular adenoma (3 papers, 2020 to 2024). A benign epithelial neoplasm arising from the hepatocytes. "The overexpression of myr-AKT1 induced lipogenesis and hepatocyte proliferation, resulting in liver hepatocellular adenomas ~12 weeks post-injection and, eventually, HCC by 6 months post-injection." (PMID 39062197, 2024).
infantile hemangioma (3 papers, 2020 to 2022). "Thus, AKT1 could be considered a therapeutic target for infantile hemangiomas and should receive more attention in recent times." (PMID 35740845, 2022). "Involuting infantile hemangioma was characterized by ACTA2 upregulation and AKT1 and MAPK14 downregulation." (PMID 35740845, 2022). "Three genes, AKT1, p38/MAPK14, and ACTA2, were found to have divergent expression in proliferating and involuting infantile hemangiomas." (PMID 35740845, 2022).
intestinal cancer (3 papers, 2019 to 2024). "The findings indicate that AKT1 is a biomarker candidate for esophageal, gastric, and intestinal cancers." (PMID 35611247, 2022). "Centrality parameters of AKT1 in the networks of esophageal, gastric, and intestinal cancers." (PMID 35611247, 2022). "Though there are several documents about the role of AKT1 in promoting of esophageal, gastric, and intestinal cancers, there is not enough evidence about the dominant role of AKT1 relative to the other oncogene genes in the promotion of the three studied cancer types." (PMID 35611247, 2022).
intraductal papilloma (3 papers, 2016 to 2025). An intraluminal papillary epithelial neoplasm arising within the ducts. "Although PIK3CA or AKT mutations are more common in breast intraductal papilloma, AKT1 E17 K mutation was detected in intraductal papilloma of minor salivary glands, and no genetic alterations (BRAF, PI3KCA etc.)were detected in salivary glands intraductal papilloma with previous reports." (PMID 40013097, 2025).
intrauterine growth restriction (3 papers, 2025). "Ubiquitous deletion of Akt1 induces intrauterine growth restriction with low placental mass, reduced glycogen cells, disorganised and fewer blood vessels and a disproportional loss of the decidua." (PMID 41258474, 2025).
left ventricular hypertrophy (3 papers, 2016 to 2023). Enlargement of the LEFT VENTRICLE of the heart. "Upon induction of dominant negative mitochondrial AKT1, CAMDAKT mice developed cardiac fibrosis accompanied by left ventricular hypertrophy and dysfunction." (PMID 37891673, 2023).
lymphedema (3 papers, 2022 to 2025). Excess fluid collection in tissues, causing swelling. "The relevance of the PI3K/AKT pathway in the etiopathogenesis of lymphedema is underlined by several studies that couple gain-of-function mutations in AKT1 and PI3KA with syndromic lymphatic malformations." (PMID 35806420, 2022).
lymphoid neoplasm (3 papers, 2014 to 2023). A neoplasm composed of a lymphocytic cell population which is usually malignant (clonal) by molecular genetic and/or immunophenotypic analysis. "To examine the therapeutic role of Akt isoform specific inhibitors in the treatment of GC-resistant lymphoid tumor cells, we treated CCRF-CEM cells with DEX and A-674563 (Akt1 inhibitor), CCT128930 (Akt2 inhibitor), or Akti1/2 (Akt1/2 inhibitor)." (PMID 30598523, 2019). "Pharmacologic inhibition of Akt2 more effectively restores sensitivity to GCs than inhibition of Akt1 in vitro, shows higher synergistic effect acting with DEX, and reverses GC resistance in GC-resistant T- or B- lymphoid tumors in vivo with reduced liver toxicity." (PMID 30598523, 2019).
malnutrition (3 papers, 2020 to 2025). Inadequate nutrition resulting from poor diet, malabsorption, or abnormal nutrient distribution. "Mice with AKT1 gene defects show abnormalities in placental development, including reduced angiogenesis, malnutrition, absence of glycogen cells in spongiotrophoblasts, and reduced decidua basalis." (PMID 39858245, 2025).
Merkel cell carcinoma (3 papers, 2012 to 2019). "Analysis of PIK3CA, AKT1 and pAKT T308 in Merkel cell carcinoma." (PMID 22363598, 2012).
myasthenia gravis (3 papers, 2022 to 2024). Myasthenia gravis (MG) is a rare, clinically heterogeneous, autoimmune disorder of the neuromuscular junction characterized by fatigable weakness of voluntary muscles. "It further indicates that the QSDH drug formulary can treat myasthenia gravis by acting on the AKT1 target protein." (PMID 36225188, 2022).
myocarditis (3 papers, 2019 to 2025). Myocarditis is a condition that is characterized by inflammation of the heart muscle (myocardium). "Inhibition of Akt1 aggravates the autophagic response caused by CVB3 infection in Akt1-overexpressing cells.These indicate that Akt played an important role in myocarditis, regulating Akt may have a therapeutic effect on myocarditis." (PMID 32128091, 2019).
nephritis (3 papers, 2015 to 2023). Inflammation of renal tissue. "After identifying the main targets (TNF, AKT1 and PTGS2) of SHP in nephritis treatment, we further conducted a KEGG analysis to reveal the signal pathways of these main targets." (PMID 37361210, 2023). "The results showed that TNF, AKT1 and PTGS2 were the main targets of SHP in treating nephritis, which was consistent with previous reports." (PMID 37361210, 2023). "Our results demonstrated that TNF, AKT1 and PTGS2 might be the key targets of SHP in the treatment of nephritis." (PMID 37361210, 2023). "Thus, the regulation of TNF, AKT1 and PTGS2 may contribute to the treatment of nephritis." (PMID 37361210, 2023).
nonalcoholic steatohepatitis (3 papers, 2022 to 2025). "The study uses metabolic dysfunction-associated steatohepatitis (MASH)-HCC and HCC mouse models established by transfecting the livers using myr-AKT1, NRasV12, and Sleeping Beauty transposase." (PMID 39953622, 2025). "KEGG enrichment analysis revealed an enrichment of the NAFLD pathway, suggesting that SLXG may potentially treat nonalcoholic steatohepatitis (NASH) by regulating the expression of genes such as CXCL8, AKT1, SREBF1, IL6, PPARA, and ADIPOQ." (PMID 39928768, 2025).
placental insufficiency (3 papers, 2011 to 2024). Failure of the placenta to deliver an adequate supply of nutrients and oxygen to the fetus. "AKT1‐deficient pregnant mice had marked placental dystrophy, reduced basement membranes, loss of saccharide‐containing cells in spongy trophoblasts, and reduced blood vessel formation, leading to placental insufficiency and impaired fetal development." (PMID 39162596, 2024).
Pruritus (3 papers, 2023 to 2025). Pruritus is an itch or a sensation that makes a person want to scratch. "Clearly, some genes such as AKT1, ALB, BCL2, STAT3, JUN, ESR1, and TNF hold important positions within the network, indicating their strong relevance to the pathogenesis of pruritus and their potential as key targets for drug intervention." (PMID 39606625, 2024).
rectal tumors (3 papers, 2019 to 2024). "CYT-high rectal tumors on the other hand, had recurrent deletions at loci 3p21.31 (RHOA), 5q22.2 (APC), 10q26.2 (MGMT), 14q32.2 (AKT1, EIF5, YY1), 18q21.2 (SMAD4, MAPK4), and a single amplification in 7p15.3 (STK31)." (PMID 31429779, 2019).
renal failure (3 papers, 2021 to 2025). "Relevant literature have shown that IL6, AKT1, VEGFA, FN1, TIMP1, ALB and TNF are associated with renal insufficiency." (PMID 36209090, 2022).
sarcoidosis (3 papers, 2020 to 2026). Sarcoidosis is a multisystemic disorder of unknown cause characterized by the formation of immune granulomas in involved organs. "Previous studies demonstrated both reduced proliferative response and exhaustion of T cells in progressive sarcoidosis is thought to be driven in part by inhibition of PI3K/AKT1 signaling." (PMID 39080656, 2024). "Our miRNA results demonstrate AKT1 as a target of downregulated miRNAs (miR-143-3p and miR-199a/miR-199b) in sarcoidosis." (PMID 39080656, 2024).
Thrombocytopenia (3 papers, 2024 to 2025). A reduction in the number of circulating thrombocytes. "AKT1 facilitates the phosphorylation of BAD, a Bcl-2 family member, inhibiting its pro-apoptotic function and liberating the anti-apoptotic protein Bcl-XL, which safeguards B cells from apoptosis and may worsen thrombocytopenia." (PMID 41353393, 2025).
thymic lymphoma (3 papers, 2019 to 2024).
Ureteral obstruction (3 papers, 2020 to 2024). Obstruction of the flow of urine through the ureter. "An existing report unveiled that the deletion of AKT1 accelerated kidney fibrosis through the activation of TGF-β1/STAT3 signaling in a mouse model of unilateral ureteral obstruction (UUO)." (PMID 36866869, 2023).
adrenal tumor (2 papers, 2023 to 2025). "Genetic mutations are common in PMEC, and in this case, molecular typing of the lung tumor tissue, adrenal tumor tissue, and plasma samples all revealed the presence of BRAF p.V600E, AKT1, and NFE2L2 mutations." (PMID 40896440, 2025). "In this case, NGS of the lung tumor tissue, adrenal tumor tissue, and plasma revealed positive BRAF p.V600E, AKT1, and NFE2L2 mutations, which are common genetic mutations." (PMID 40896440, 2025).
Angiomatous Meningioma (2 papers, 2014 to 2025). A WHO grade I meningioma characterized by the presence of small and medium sized vessels that predominate over the meningioma cells. "Mutations in AKT1, KLF4, POLR2A or SMO were mostly detected in meningothelial or transitional meningioma, except for three cases: one case of angiomatous meningioma with KLF4 mutation, one case of secretory meningioma with KLF4 mutation and one case of psammomatous meningioma with AKT1 mutation." (PMID 40815185, 2025).
aortic aneurysm (2 papers, 2015 to 2021). A ruptured aneurysm located in the wall of the proximal portion of the descending aorta proceeding from the arch of the aorta. "Although we previously showed that AKT-2 plays a protective role in the aorta and identified decreased AKT-2 protein levels in sporadic aortic aneurysm tissue, in the present study we found no differential expression of AKT1 or AKT2 in SMCs or fibroblasts in MFS compared to controls." (PMID 35052435, 2021).
cannabis abuse (2 papers, 2012 to 2016). "Antipsychotic medication and nicotine or cannabis abuse were considered as possible confounders affecting the expression of AKT1." (PMID 22393424, 2012). "So, our findings of decreased AKT1 expression in antipsychotic-naïve patients, and in those with cannabis abuse, should be interpreted with caution." (PMID 22393424, 2012). "Also in these cases, if any, patients with nicotine or cannabis abuse tended towards higher level of AKT1 expression." (PMID 22393424, 2012).
cardiac arrest (2 papers, 2017 to 2019). Cessation of breathing and/or cardiac function. "Lactate, the conventional metabolic marker in the blood related to cardiac arrest injury, was increased from 0.52 ± 0.08 mmol/L in sham to 4.06 ± 0.48 mmol/L at R30 with NT in Akt1+/+ mice." (PMID 31398213, 2019). "Given the recognized role of inflammation in cardiac arrest injury, we measured markers of inflammation that may be related to Akt1 downstream signaling." (PMID 31398213, 2019). "Next, to validate the expression of AKT1, BCL2, and MAPK3 in the large cohort of cardiac arrest patients, we recapitulated gene expression levels of AKT1, BCL2, and MAPK3 in the datasets available from the NCBI, GEO database (GSE29540)." (PMID 28147324, 2017). "For Akt1+/- mice, 9 out of 10 mice in the NT group and 10 out of 10 mice achieved ROSC, similar to Akt1+/+ mice suggesting that TH had minimal effect on ROSC rates with this duration of cardiac arrest." (PMID 31398213, 2019).
cervical squamous cell carcinoma (2 papers, 2021 to 2024). A squamous cell carcinoma arising from the cervical epithelium. "Additionally, the positive correlation between HK2 and Akt1 expression in cervical squamous cell carcinoma and endocervical adenocarcinoma (CESC) was confirmed from the GEPIA online database." (PMID 34758823, 2021).
Chagas disease (2 papers, 2018 to 2021). A parasitic infection caused by Trypanosoma cruzi. "Our findings indicate that canonical PI3Kγ/AKT1 signaling is upregulated in the heart tissue of T. cruzi-infected mice and humans with the Chagas disease." (PMID 29666415, 2018).